Y_RNA (Y RNA )
Gene: Miscellaneous RNA gene on chromosome 12 (113,178,423 to 113,178,519, reverse strand). Ensembl gene ENSG00000201208.
Homologues: Orthologues: chimpanzee Y_RNA (100% identical), macaque Y_RNA (95% identical), guinea pig Y_RNA (88% identical). Paralogues in human: RNY4P25 (88% identical), RNY4 (87% identical), RNY4P19 (87% identical), Y_RNA (87% identical), RNY4P24 (86% identical), Y_RNA (86% identical), RNY4P37 (85% identical), RNY4P6 (85% identical), RNY4P7 (85% identical), Y_RNA (85% identical), RNY4P10 (84% identical), Y_RNA (84% identical), and 90 more.